IDH1 (isocitrate dehydrogenase (NADP(+)) 1)
Diseases named in the same sentence as IDH1 in open-access papers (continued):
Sharing a sentence is not in itself a finding about the gene and the disease.
glioma (continued). "The IDH1 R132H mutation was detected in 80% of gliomas of OD patients and simultaneously in enchondromas and gliomas in 100% of cases." (PMID 35884525, 2022). "Significant differences between IDH1-mutated and IDH1-wildtype gliomas were revealed for maximum, lower percentiles, modus, standard deviation (SD), entropy and skewness." (PMID 35884457, 2022). "IDH1 mutations produce a distinct metabolite, 2-hydroxyglutarate (2HG), promoting a hypermethylation phenotype in gliomas." (PMID 35806212, 2022). "It has been reported that D-2HG competitively inhibits PHDs due to its structural similarity to α-KG, thereby causing accumulation of HIF-1α in IDH1-mutant glioma cells." (PMID 35198082, 2022). "The results of this study showed that gliomas with low expression of PLK4 had a higher number of IDH1 mutations (46%) as compared to those with high expression of PLK4 (22%)." (PMID 36620611, 2022). "Current World Health Organization diagnostic classification schemes for adult infiltrating gliomas are based on the presence of molecular alterations such as isocitrate dehydrogenase 1/2 mutations (IDH1/2) and 1p/19q codeletion." (PMID 35455749, 2022). "We identified significant associations between age-associated SNVs and mRNA abundance for ATRX and IDH1 in lower grade glioma." (PMID 35017538, 2022). "Mutations in isocitrate dehydrogenase 1 (IDH1) are frequently found in gliomas and are associated with better therapeutic outcomes." (PMID 35406593, 2022). "In the 2016 World Health Organization (WHO) glioma grading system, isocitrate dehydrogenase-1 (IDH-1) gene mutation was included for identifying malignancy grade in glioma." (PMID 35887658, 2022). "The pooled OR for IDH1 mutation in the CIMP + versus CIMP- glioma revealed a significantly higher risk of IDH1 mutation in the CIMP + glioma (OR 229.07; 95% CI 138.72–378.26; P < .00001, Pheterogeneity 0.000)." (PMID 36181110, 2022). "Their research showed that IDH1 mutation and CIMP were independent predictors of outcome, suggesting that CIMP and IDH1 mutation are potential prognostic biomarkers in glioma." (PMID 36181110, 2022). "Pharmacologic inhibition of the nuclear factor erythroid 2-related factor 2/glutathione pathway via brusatol administration exhibited a potent tumor suppressive effect on IDH1-mutated glioma in vitro and in vivo." (PMID 36221066, 2022). "Gliomas carrying IDH1 mutations employ a PYCR1-driven proline synthesis pathway to maintain a lower NADH/NAD ratio." (PMID 36295820, 2022). "While 82% of cases in low‐risk group carried IDH1 mutation, which represented an earlier driven mutation in the glioma and indicated a better prognostic outcome." (PMID 35985661, 2022). "Gliomas expressing the IDH1 mutation are associated with better chemo- and radiotherapy responses and longer patient survival periods." (PMID 35303961, 2022). "Most sporadic adult diffuse grade II and III gliomas harbor mutations of the IDH1 and/or IDH2 genes, which is considered the first event driving oncogenesis of these tumors." (PMID 35884525, 2022). "Whilst several studies have used magnetic resonance imaging (MRI) to attempt to non-invasively characterize the IDH1 mutation in gliomas (, the potential for positron emission tomography (PET) as a complementary metabolic imaging tool, is a growing field." (PMID 35303961, 2022). "In glioma, mutations in IDH1/2 lead neoconversion of α-KG into the oncometabolite D-2-hydroxyglutarate (D-2-HG)." (PMID 35455749, 2022). "The primary aim of INDIGO is to prolong the time from diagnosis after surgery to the need for subsequent cytotoxic treatments in patients with residual or recurrent grade 2 gliomas with an IDH1 or IDH2 mutation between 1 and 5 years after the last surgery." (PMID 35692047, 2022). "A phase II study of the ivosidenib–nivolumab association in advanced IDH1 mutated solid tumors, including contrast-enhancing gliomas, is recruiting (NCT04056910)." (PMID 35267432, 2022).
glioma (continued). "IDH1 is highly expressed in low-grade gliomas and in recurrent GBM, where more than 90% of IDH1 mutations occur at codon 132 containing the R132H mutation." (PMID 35628161, 2022). "In IDH1 mutated glioma, a multicenter open-label phase I dose escalation study of ivosidenib showed a favorable safety profile as well." (PMID 35158978, 2022). "It has been extensively documented that while histone H3 and IDH1 mutation status are the main identifiers for pediatric high grade-glioma (HGG) and DIPG subgroups there are other secondary mutations within these subgroups that drive disease progression." (PMID 35590427, 2022). "Therapeutic schemes remain very similar for every patient, although, according to the 2021 WHO classification, gliomas split into three types: IDH1-mutated/1p/19q-codeleted oligodendroglioma, IDH1-mutated astrocytoma, or IDH1 wild-type glioblastoma." (PMID 36077653, 2022). "In this context, glutamate reduction contributes to better outcomes represented by gliomas with the IDH1 mutation." (PMID 36289655, 2022). "It is known that glial tumor cells with an IDH1 mutation adjust the production of energy in the Krebs cycle due to the super-expression of LDH1.2 (with the formation of pyruvate)." (PMID 35625744, 2022). "The presence of the IDH1 mutation in glioma predicts a favourable disease outcome with prolonged median survival." (PMID 36292072, 2022). "When the IDH2 variant occurs in gliomas, in almost all of the cases, it consists of a substitution of the arginine at codon 172, which is the exact residue analogous to Arg132 in IDH1." (PMID 35456430, 2022). "For example, approximately 20–30% of infiltrative gliomas carry mutations in isocitrate dehydrogenase 1 (IDH1) or, far less commonly, IDH2 (together referred to as “IDHmut”)." (PMID 35134075, 2022). "A phase II study in patients with chemotherapy and radiotherapy naïve IDH1-mutated grade 2 glioma is ongoing (NCT04458272)." (PMID 35267433, 2022). "Among the six IDH-mutant gliomas, three had the same IDH1 mutation detected in plasma (50%), and the IDH1-positive ctDNA result was obtained in patients either at diagnosis (no treatment) or during progressive disease." (PMID 35740557, 2022). "According to the WHO classification guidelines for central nervous system tumors (2021 edition), gliomas are classified by IDH1/2 mutation and 1p/19q codeletion." (PMID 35493457, 2022). "In this regard, Cyn exhibited high cytotoxicity on the U-87 MG IDH1 R132H mutant glioblastoma cell line, the most common mutation in glioma, dramatically affecting the cell metabolism and morphology, with an IC50 lower than IDH wild-type U-87 MG." (PMID 35884887, 2022). "The TCGA and CGGA data showed that MAN2B1 expression was significantly upregulated in glioma tissues and was associated with WHO grade, IDH1 mutation status, and histological subgroups of glioma patients." (PMID 35186771, 2022). "For example, in cluster 1, most glioma samples harbored IDH1 mutation, which was included in the tricarboxylic acid cycle and interreacted with purine metabolism." (PMID 36438805, 2022). "The maximum mutation’s frequency of IDH1 is more than 90% in gliomas, while the mutation’s frequency of IDH2 is less than 5%." (PMID 36091829, 2022). "Significant differences in neuropsychological performance were observed between patients with IDH-1 mutated gliomas and wild-type." (PMID 35720068, 2022). "Although IDH1 plays a crucial role in carcinogenesis (gliomas) and has a polymorphism character, it is still unclear how identified nsSNPs alter the protein’s structure and biological activity." (PMID 36188571, 2022). "In contrast, we observed a JQ1-mediated selective cytotoxic response associated with R132H IDH1 in our endogenous IDHmut glioma cells (0905, BT142) and dox-inducible R132H IDH1 model that is little observed in the IDHwt counterpart (0827, 0923)." (PMID 35467128, 2022).
glioma (continued). "By excluding IDH1/2-mutated patients, we reduced the risk of enrolling patients suffering from low-grade glioma with different prognoses, microenvironments, and biology." (PMID 35741816, 2022). "The discovery of the IDH1 mutation (frequently found in low-grade gliomas and secondary high-grade gliomas) has brought additional focus and attention to the problem of epigenetic dysregulation in gliomas." (PMID 35581287, 2022). "IDH1/2 gene mutation was first recognized in the AML as well as glioma and afterward in numerous other cancers." (PMID 35873570, 2022). "A sequence of human tumors for IDH1 or IDH2 mutations, or monoclonal antibodies against the most common IDH1 mutation (R132H), allows for immunohistochemical analysis of low-grade gliomas and GBMs." (PMID 35806212, 2022). "This sequence does not require the injection of exogenous contrast, and is utilized in certain studies to attempt to characterize glioma grade and IDH1 mutational status." (PMID 35281485, 2022). "Isocitrate dehydrogenase (IDH1) is frequently mutated in glioma tissues, and this mutation mediates specific tumor-promoting mechanisms in glioma cells." (PMID 36159801, 2022). "The levels of glutathione peroxidase in the peritumoral zone tissue of patients with gliomas and the IDH1 mutation were significantly higher than in the wild-type IDH1 group." (PMID 36289655, 2022). "Typical chromosomal alterations for high grade gliomas include amplification of chromosome 7 and 19, and loss of chromosome 1018, while IDH1-mutant gliomas more frequently loose 1p/19q and gain chromosomes 8 and 1019,20." (PMID 36348001, 2022). "For example, the IDH1 mutation status has long been recognized as a very important prognostic biomarker for glioma." (PMID 35093128, 2022). "IDH1 mutation is one of the most common and earliest detected genetic alterations in diffuse gliomas, and evidence supports this mutation as a driver of glioma development." (PMID 35571123, 2022). "In 2016, WHO added molecular informatics including IDH1 mutations to the classification of central nervous system tumors on a histological basis." (PMID 36246611, 2022). "When this manuscript was under preparation, a group reported that TPL serves as NRF2 inhibitor and exhibits selective cytotoxicity in IDH1-mutated glioma cells." (PMID 34108030, 2021). "The importance of IDH1/2 mutations in glioma is reflected by the fact that, since 2016, they have featured as diagnostic criteria in the World Health Organization’s (WHO) categorization of central nervous system (CNS) tumors." (PMID 35028610, 2021). "AGI-5198 was reported to inhibit the accumulation of 2-HG in IDH1-mutated glioma cells in vivo, that also promoted the differentiation of glioma cells." (PMID 34680164, 2021). "Previous studies suggested that IDH1 mutation is a powerful prognostic marker for gliomas, and it is also considered as a predictive biomarker for extensive surgical resection, radiotherapy and chemotherapy in gliomas." (PMID 33472598, 2021). "Glioma patients were divided into IDH1 mutation group and IDH1 wild-type group and the association between UBE2S expression level and the IDH1 status was determined." (PMID 34123793, 2021). "In the present study, we assessed the clinical impact of non-canonical IDH1 mutation on a population of patients with WHO grade II–III IDH1 mutant gliomas." (PMID 33669525, 2021). "Numerous studies showed that IDH1 mutations lead to better overall survival in gliomas patients and better response to therapies." (PMID 34070746, 2021). "IDH1/2 mutations and 1p19q co-deletion, the 2 crucial mutations in glioma, are associated with favorable prognosis in glioma patients." (PMID 34362400, 2021). "For example, reduced expression of isocitrate dehydrogenase 1 (IDH1) in glioma models is associated with increased PC and decreased pyruvate dehydrogenase (PDH) activity." (PMID 33931119, 2021).
glioma (continued). "As reflected by a lower ALPS index, glymphatic function was impaired in IDH1 wild-type gliomas and gliomas associated with larger peritumoral brain edema volumes." (PMID 34631582, 2021). "IDH1 mutations were thought to control the balance between glioma stem cell property and cell differentiation." (PMID 34490090, 2021). "Our findings revealed that oral microbiota features and gene functions are associated with glioma malignancy and the IDH1 mutation." (PMID 34733261, 2021). "Elevated 2HG levels in IDH1/2-mutated glioma are taken up by the stromal cells in the microenvironment." (PMID 33804873, 2021). "A previous study reported that glioma cells with IDH1 mutation produce 2-hydroxyglutarate, which promotes HIF-1α degradation, accompanied by the downregulation of glycolysis-related genes including SLC2A1, PDK1, LDHA, and SLC16A3." (PMID 33627136, 2021). "Mutations in the isocitrate dehydrogenase 1 (IDH1) gene occur in high-grade chondrosarcoma, high-grade glioma and intrahepatic cholangiocarcinoma." (PMID 34069550, 2021). "IDH mutations are thought to occur early on in the genesis of a glioma with the most common heterozygote mutation being IDH1 Arg 132 (R132H)." (PMID 33477674, 2021). "Initially, IDH1 mutated glioma cells have been reported to produce lower amounts of α-KG in favor of D-2-HG, leading to HIF-1α overexpression." (PMID 34073734, 2021). "In gliomas, it has been shown that mutation of a single gene, IDH1, establishes G-CIMP by remodeling and reorganization of the methylome and transcriptome." (PMID 33572577, 2021). "The (IDH1) R132H peptide vaccine targets a frequently occurring mutation in the IDH1 gene found primarily in lower grade gliomas, which is responsible for aberrant neural signaling and glioma progression." (PMID 33496872, 2021). "The protein level of B7H3 is positively correlated with VEGFA, and both proteins are reduced in IDH1-mutated glioma samples and further decreased in 2-HGhigh gliomas." (PMID 34079802, 2021). "A lower ALPS index was associated with IDH1 wild-type gliomas and larger peritumoral brain edema volume." (PMID 34631582, 2021). "Many MR imaging markers have been found to be useful in predicting the IDH1 mutation status in gliomas." (PMID 34631582, 2021). "In summary, the present study indicated that oral microbiota composition and gene functions are significantly associated with glioma malignancy and the IDH1 mutation." (PMID 34733261, 2021). "Based on the differences in clinical behavior displayed by glioma patients and their distinctive tumor transcriptional profiles, IDH1/2 mutations were integrated into the molecular classification of these tumors." (PMID 34948178, 2021). "This is the first clinical trial to describe the toxicity profile, safety and pharmacokinetics of the combination of metformin and chloroquine in patients with IDH1-mutated chondrosarcoma, glioma and intrahepatic cholangiocarcinoma." (PMID 34069550, 2021). "Here, we investigated the genetic background of IDH1-mutant gliomas using the Catalogue of Somatic Mutations in Cancer (COSMIC) database." (PMID 34503108, 2021). "In this context, reduced Glu contributes to a better outcome presented by gliomas with IDH1 mutation." (PMID 33910646, 2021). "Metabolomics analysis through Capillary electrophoresis time-of-flight mass spectrometry (CE-TOFMS) revealed that levels of D-2-hydroxyglutarate (D-2HG) were significantly increased in the glioma patients with an IDH1 mutation." (PMID 34150663, 2021). "IDH1/2 mutations are also detected in solid tumors (e.g., glioma, colorectal, breast, renal cancers) and in an IDH1 mutated colorectal cancer cell line, treatment with vitamin C synergized with an IHD1 inhibitor by rescuing TET activity." (PMID 33804775, 2021).
glioma (continued). "Mutant IDH1 in gliomas causes broad epigenetic alterations, including DNA hypermethylation, and results in a subtype of glioma with a CpG island methylator phenotype (G-CIMP)." (PMID 33663520, 2021). "The most common IDH1 mutation in gliomas affects codon 132 and encodes IDH1(R132H), which harbours a shared clonal neoepitope that is presented on major histocompatibility complex (MHC) class II4,5." (PMID 33762734, 2021). "In order to clarify the influence of IDH1 mutation on glucose consumption and the level of glucose in gliomas, we compared the expression of key gluconeogenesis and glycolysis enzymes in clinical tissues." (PMID 33472598, 2021). "Small populations of IDH2-mutated gliomas were identified as well, with 6% (18/281) of IDH1/2-mutated gliomas harboring IDH2 R172 mutations." (PMID 33778493, 2021). "IDH1/2 mutations are common in glioma cells and can completely change the DNA methylation landscape." (PMID 33828990, 2021). "DNA methylation in CpG islands define the CpG island methylator phenotype (G-CIMP), a hallmark of mutant-IDH1 glioma, which is linked to better prognosis." (PMID 34422657, 2021). "Subsequent study identified that IDH1/IDH2 mutations were more prevalent in WHO grade II/III glioma than GBM, and patients occurred IDH gene mutations share a better outcome than those of wildtype IDH genes." (PMID 34121368, 2021). "Using samples from Xiangya hospital, we found the consistent results that glioma patients with histological type of astrocytoma, wild-type IDH1, and unmethylated MGMT had higher risk scores." (PMID 34805164, 2021). "Consistent with our results, IDH1/2 mutations have been shown to be factors indicating a favorable prognosis in all types of gliomas." (PMID 34552618, 2021). "IDH1/2 pathogenic variants are considered prognostic biomarkers in subjects with glioma and are associated with more prolonged overall survival." (PMID 34858308, 2021). "For example, in IDH1 mutated glioma, we have shown that methylation in PD-L1 promoter negatively correlates with PD-L1 expression and prognosis." (PMID 34168976, 2021). "Non-invasive and accurate prediction of IDH1 mutation in glioma has great potential in routine clinical application." (PMID 33472598, 2021). "The incorporated diagnostic biomarkers in the 2016 WHO classification of gliomas were Isocitrate dehydrogenase (IDH)-1/2 mutations, 1p/19q codeletion, H3 Histone, Family 3A (H3F3A) or HIST1H3B/C K27M (H3-K27M) mutations, and C11orf95–RELA fusions." (PMID 35008238, 2021). "First, we investigated the relationship between PACSIN1 and clinical indicators of gliomas (grades, IDH1 mutation status, 1p/19q codeletion status and different molecular subtypes defined by TCGA network)." (PMID 34422904, 2021). "An increasing number of molecular biomarkers, such as TERT promoter mutation, IDH1/2 mutation and 1p/19q co-deletion, have been used in clinic of glioma." (PMID 33557829, 2021). "R132 of IDH1 is a hotspot somatic mutation site that has been reported to be the leading cause of chondrosarcoma/chondromas, gliomas/glioblastomas and some type of AML." (PMID 34790172, 2021). "IDH1 mutation status was considered the basis for glioma diagnosis according to the 2016 WHO classification of CNS tumours." (PMID 34804371, 2021). "2HG detected non-invasively in glioma patients with IDH1 mutationtwo-dimensional (2D) correlation magnetic resonance spectroscopy (MRS) was capable to detect 2HG in vivo." (PMID 34150663, 2021). "Low-grade gliomas (p = 0.006), IDH1 mutation (p = 0.040) and low Ki-67 expression (defined as a Ki-67 index <10%, p = 0.005) were identified to be associated with a higher incidence of new-onset postoperative seizures." (PMID 34220689, 2021). "In agreement with our earlier observations, B7H3 and VEGFA were significantly decreased in IDH1-mutated gliomas compared to that in IDH1-WT glioma samples." (PMID 34079802, 2021).